STAT6 (signal transducer and activator of transcription 6)
Diseases named in the same sentence as STAT6 in open-access papers (continued):
Sharing a sentence is not in itself a finding about the gene and the disease.
angiosarcoma (3 papers, 2021 to 2025). A malignant tumor arising from the endothelial cells of the blood vessels. "The tumor cells were negative for desmin, HHF35, HMB45, Melan A, MITF, c-kit, DOG1, cytokeratin AE1/AE3, h-caldesmon, STAT6, CD68, CD31, Factor 8, and ERG, making diagnoses of PEComa, GIST, SFT, and angiosarcoma unlikely." (PMID 34797454, 2021).
cervical cancer (3 papers, 2023 to 2025). A primary or metastatic malignant neoplasm involving the cervix. "The role of STAT6 in cervical cancer is poorly studied, and very few reports indicate that HeLa cells express STAT6 constitutively and that a small proportion is in its phosphorylated form." (PMID 37372319, 2023).
chronic obstructive pulmonary disease (3 papers, 2019 to 2022). A chronic and progressive lung disorder characterized by the loss of elasticity of the bronchial tree and the air sacs, destruction of the air sacs wall, thickening of the bronchial wall, and mucous accumulation in the bronchial tree. "Moreover, the hyperactivity of the IL-4/STAT6 pathway is associated with asthma and chronic obstructive pulmonary disease, and the transcriptional inhibitors of this pathway are potential targets for the prevention and treatment of diseases caused by the hyperactivity of the IL-4/STAT6 pathway." (PMID 33228696, 2020). "Liuweibuqi capsules were reported to be effective in treating chronic obstructive pulmonary disease (COPD) through antagonizing STAT4, but activating STAT6." (PMID 36324680, 2022).
cyst (3 papers, 2023 to 2025). A sac-like closed membranous structure that may be empty or contain fluid or amorphous material. "Using short-hairpin RNA (shRNA) knockdowns in human foreskin fibroblasts (HFFs) and PNCs from transgenic mice, we determined that ROP16’s cyst enhancing abilities are mediated, in part, by phosphorylation—and therefore activation—of the host cell transcription factor STAT6." (PMID 37068104, 2023). "As the STAT6 knock-down showed the strongest effect on cyst formation and STAT6KO mice are commercially available, we decided to test the role of STAT6 in cyst development using PNCs from STAT6KO mice." (PMID 37068104, 2023). "To determine if the type III ROP16 encystment defect was solely mediated by STAT6, we infected STAT6KO PNCs with WTIII, IIIΔrop16, or the ROP16III complement and tracked cyst formation over time." (PMID 37068104, 2023). "Rop16-type I/III, but not type II, phosphorylates host STAT3 and STAT6, promoting early M2 macrophage polarization and reduced IL-12 secretion, favoring cyst formation." (PMID 41472067, 2025). "Taken together these results indicate that STAT6 enhances cyst development in HFFs and PNCs for type III strains, but not type II strains." (PMID 37068104, 2023). "To test the role of STAT6 in vivo, we infected wild-type (WT) and STAT6KO mice, finding that, compared to WT mice, STAT6KO mice have a decrease in CNS cyst burden but not overall parasite burden or dissemination to the CNS." (PMID 37068104, 2023).
gastrointestinal stromal tumor (3 papers, 2024 to 2025). "Bcl-2 and vimentin are typically immunoreactive in SFTs in addition to CD34 and STAT6, but SMA and desmin (a marker for myocytes), S-100 and synaptophysin (a marker for perineural tissue), or c-kit (a marker for gastrointestinal stromal tumors) are generally negative." (PMID 39435031, 2024).
head and neck cancer (3 papers, 2013 to 2018). A primary or metastatic malignant neoplasm affecting the head and neck. "In head and neck cancer tumor patients, STAT6 expression is correlated with an improved clinical outcome for patients receiving platinum-based radiochemotherapy." (PMID 25006835, 2014).
Hepatitis (3 papers, 2024 to 2025). Inflammation of the liver. "Mechanistically, infiltration of neutrophils and eosinophils in ConA-induced hepatitis is inhibited in STAT6-deficient mice compared to WT mice, suggesting that STAT6 plays a critical role in ConA-induced hepatitis." (PMID 41409600, 2025).
Kaposi's sarcoma (3 papers, 2021 to 2025). A malignant neoplasm characterized by a vascular proliferation which usually contains blunt endothelial cells. "In summary, Tat-mediated lytic activation increases the risk and severity of Kaposi’s sarcoma, whereas LANA/STAT6–mediated latency promotes the survival of infected cells and viral persistence." (PMID 41009690, 2025).
latent infection (3 papers, 2017 to 2025). "To test the role of STAT6 in latent infection, we infected STAT6KO mice and BL6 control mice with the WTIII parasites and harvested brains at 17 dpi." (PMID 37068104, 2023). "However, the identification of STAT6 as a downstream mediator of the ROP16 encystment phenotype in vitro opened an avenue for assessing the role of STAT6 during latent infection in vivo." (PMID 37068104, 2023). "Western blot analysis of nuclear and cytoplasm fractionation further confirmed the role of LANA in induction of STAT6 nuclear localization and cleavage, indicating that nuclear localization and cleavage of STAT6 is induced by LANA in response to KSHV latent infection." (PMID 28099521, 2017). "To determine whether ARG1 induction during Cryptococcus latent infection is due to cell-intrinsic STAT6 signaling, we generated mixed bone marrow chimeras whereby congenic markers can be utilized to recognize the genotype of cells competed in the same recipient." (PMID 40568097, 2025).
leiomyoma (3 papers, 2007 to 2024). A well-circumscribed benign smooth muscle neoplasm characterized by the presence of spindle cells with cigar-shaped nuclei, interlacing fascicles, and a whorled pattern. "They included several genes such as NR2F1, PNN, Smad4, Smad5, STAT5B, JUN, TGIF2, and ATF1 that were over-expressed while RUNX3, STAT1, STAT6, EGR3, GAS7, Smad1, and EDF1 were underexpressed in leiomyomas as compared to keloid/incisional scars." (PMID 17718906, 2007).
lymph node metastasis (3 papers, 2019 to 2023). "Furthermore, high STAT6 expression is associated with lower survival rates and lymph node metastasis." (PMID 38201452, 2023). "Also, the expression of STAT6 is correlated with lymph node metastasis and distant metastasis (p = 0.001 and p = 0.016, respectively)." (PMID 31718693, 2019).
malignant peripheral nerve sheath tumor (3 papers, 2014 to 2020). Malignant peripheral nerve sheath tumor (MPNST) is a rare and often aggressive soft tissue sarcoma occurring in a wide range of anatomical sites. "The cases of malignant peripheral nerve sheath tumour we used as controls were S-100 and Sox-10 positive, while STAT6 was negative." (PMID 32566457, 2020).
myocardial infarction (3 papers, 2021 to 2024). Gross necrosis of the myocardium, as a result of interruption of the blood supply to the area, as in coronary thrombosis. "In the LAD ligation of a rat model, as early as 5 minutes after myocardial infarction, we observed JAK2, STAT1, STAT3, STAT5a, and STAT6 phosphorylation." (PMID 34516361, 2021). "Another study, though in a non-tumor setting of myocardial infarction recovery, illuminated the function of nucleolin (NCL) in regulating the immune response by controlling STAT6 and Notch3 pathways to promote M2 macrophage polarization, underscoring NCL's potential in modulating immune reactions." (PMID 38806553, 2024).
renal cell carcinoma (3 papers, 2018 to 2024). "For instance, IL-4 and TNF-α exert synergistic effects on the PD-L1 induction in renal cell carcinoma (RCC) by activating signaling molecules, including NF-κB, IκB, and STAT6." (PMID 34088360, 2021).
rhabdomyosarcoma (3 papers, 2021 to 2025). A rare aggressive malignant mesenchymal neoplasm arising from skeletal muscle. "In rhabdomyosarcoma cells, activation of IL4R with IL4 and IL13 ligands increased tumor growth through activation of STAT6, Akt, or MAPK pathways." (PMID 33419470, 2021).
thyroid cancer (3 papers, 2022 to 2025). "Differences in immune cell count between benign and malignant thyroid tumors were also associated with distinction in STAT6 and SMAD4 expression." (PMID 39936166, 2025). "By analyzing microarray data from the GEPIA database, we also found that POSTN levels were positively correlated with STAT3 and IL-4 is strongly linked to STAT6 in thyroid cancer." (PMID 38773979, 2024). "For instance, the recent study defined the prognostic role of the transcription factor of signal transducer and activator of transcription (STAT) family–STAT6, in thyroid cancer." (PMID 39936166, 2025). "Signal transducer and activator of transcription 6 (STAT6) is significantly positively associated with immune infiltration of B cells, CD4 T cells, neutrophils, macrophages and dendritic cells of thyroid cancer." (PMID 35185791, 2022). "Thyroid carcinomas demonstrate high immunogenicity compared to adenomas with extensive infiltration by CD8+, CD68+ and CD163+ macrophages, associated with increased expression of SMAD4 and STAT6 in tumor cells." (PMID 39936166, 2025).
acute liver failure (2 papers, 2023 to 2025). Rapid deterioration of liver function causing encephalopathy and coagulopathy. "In fact, STAT6 presents a protective role in limiting inflammatory I/R response and acute liver failure." (PMID 41409600, 2025). "According to several studies, STAT6 activation (p-STAT6) in M2 macrophages of patients with acute liver failure and in the cerebrospinal fluid of those with primary central nervous system lymphoma significantly correlates with the presence of interleukin -10 (IL-10)." (PMID 37461040, 2023).
acute lung injury (2 papers, 2021 to 2022). A condition of lung damage that is characterized by bilateral pulmonary infiltrates (pulmonary edema) rich in neutrophils, and in the absence of clinical heart failure. "Recent studies also showed the critical role of STAT6 in the development of acute lung injury (ALI) in mice and acute respiratory distress syndrome (ARDS) in patents." (PMID 35606692, 2022). "There was increased activation of STAT6 and expression of NLRP3 in mice with murine acute lung injury (ALI)." (PMID 35606692, 2022).
adenoma (2 papers, 2021 to 2025). A neoplasm arising from the epithelium. "In adenomas, about half of tumor cells showed mild cytoplasmic expression of STAT6, whereas in TC STAT6 demonstrated moderate expression in a higher proportion of tumor cells (p = 0.008)." (PMID 39936166, 2025). "To test this hypothesis, we subjected WT and STAT6−/− mice to an AOM/DSS regimen and analyzed the CAC progression at Day 20, Day 40 (early stages), and Day 68 (late stage of tumor development, where adenoma-like lesions are observed) as an approximation of different stages of tumor progression." (PMID 33919941, 2021).
Airway obstruction (2 papers, 2015). Obstruction of conducting airways of the lung. "The absence of STAT6-signaling did not significantly alter either the airway obstruction or weight loss in FI-RSV-immunized mice following RSV challenge." (PMID 25769044, 2015). "The increased airway obstruction associated with FI-RSV immunization in the absence of STAT6-signaling suggests that baseline pulmonary function remains impaired despite reduced AHR." (PMID 25769044, 2015).
airways allergy (2 papers, 2014 to 2021). "This indicates that early transient STAT6-inhibition constitutes an effective immunomodulatory airways allergy preventative strategy." (PMID 33883042, 2021).
anaplastic astrocytoma (2 papers, 2011 to 2021). "STAT6 staining was observed in 5 of 8 (62.5%) pilocytic astrocytomas (Grade I), 14 of 17 (82.3%) diffuse astrocytomas (Grade II), 5 of 5 (100%) anaplastic astrocytomas (Grade III) and 4 of 5 (83.4%) GBM." (PMID 21595984, 2011).
atopic asthma (2 papers, 2021 to 2025). An asthma that is characterized by symptoms that are triggered by an allergic reaction caused by inhaled allergens such as dust mite allergen, pet dander, pollen and mold. "This study aimed to determine the association between the STAT6 rs324011 gene polymorphism and atopic asthma among Yemeni children as well as to investigate the impact of the STAT6 rs324011 polymorphism on IL-13, total IgE, and eosinophils." (PMID 40375219, 2025). "Our findings reveal a significant association between the STAT6 rs324011 polymorphism and the risk of developing atopic asthma." (PMID 40375219, 2025). "Second, while this study provides valuable insights into the association between the STAT6 rs324011 polymorphism and atopic asthma in Yemeni children, it’s important to recognize the limitations of focusing on a single SNP." (PMID 40375219, 2025). "Under a recessive model, the TT genotype of the STAT6 polymorphism rs324011 was significantly associated with an increased risk of atopic asthma compared to the CC and CT genotypes (χ2 = 6.6, OR = 2.5, CI = 1.2–5, p = 0.01)." (PMID 40375219, 2025). "A GT repeat influencing the regulation of the promoter activity of STAT6 was associated with susceptibility to atopic asthma and total serum IgE levels." (PMID 33925531, 2021). "We hypothesized that the STAT6 rs324011 polymorphism is associated with an increased susceptibility to atopic asthma among Yemeni children, with the TT genotype conferring a higher risk." (PMID 40375219, 2025).
bladder cancer (2 papers, 2022 to 2023). "In addition, in bladder cancer cell J82 with down-regulated expression of CHAF1A, some down-regulated expression of several genes related to cell growth and proliferation were found, including STAT2, STAT6, AKT2, IRS1 and SOX4." (PMID 37575547, 2023).
cerebral aneurysm (2 papers, 2023 to 2025). "The fatal cerebral aneurysm in P10 (p.E382Q) was not clinically anticipated, but it is possible that the STAT6 GOF variant also increased the risk of developing cerebral aneurysms." (PMID 36884218, 2023).
childhood asthma (2 papers, 2012 to 2022). "Moreover, the IL4Ra and INSIG2 gene combination interacted with GSTP1, STAT6, ADRB2, ADRB3, IL13 and EPHX1 exon 3 to reveal a high training-balanced accuracy above 58.38% in childhood asthma." (PMID 22355322, 2012).
Chlamydia infection (2 papers, 2021 to 2024). "Although the transcription factor GATA3 regulates Th2 development, Gata3 null mutant mice are embryonic lethal, thus we examined Chlamydia infection of STAT6-deficient mice which lack Th2 development." (PMID 38166152, 2024). "However, STAT6-/- mice were vulnerable to Chlamydia infection, thus revealing that IL-4-mediated STAT6 signaling pathway triggered and induced the infection." (PMID 34226412, 2021). "Thus, mice lacking T-bet, STAT6, or CD4-derived IFN-γ can fully resolve Chlamydia infection in the FRT." (PMID 38166152, 2024).
chronic asthma (2 papers, 2018 to 2023). An asthma that is characterized by the development of persistent airway inflammation and recurrent attacks of breathlessness and wheezing, which vary in severity and frequency. "Such as olaparib significantly reduces the protein expression of STAT‐6 and GATA‐3, inhibits the inflammasome signaling, and reduces the remodeling characteristics associated with chronic asthma in mice." (PMID 37904699, 2023).
chronic kidney disease (2 papers, 2021 to 2022). Impairment of the renal function secondary to chronic kidney damage persisting for three or more months. "Therefore, targeting STAT6 with AS1517499 is a novel therapeutic approach for chronic kidney disease." (PMID 34512669, 2021). "For instance, recent studies suggest that the role of M2 macrophages in chronic kidney disease may be the opposite of that in AKI, and targeting signal transducer and activator of transcription 6 (STAT6) can inhibit the polarization of M2 macrophages, thereby protecting renal function." (PMID 35755446, 2022).
co-infection (2 papers, 2021 to 2023). "IL-13 expression was predominant in dogs infected with D. repens, and STAT6 and IL-10 predominated in dogs with co-infections." (PMID 36739305, 2023). "The expression of IL-13 was predominant in dogs infected with D. repens, and the expression of STAT6 and regulatory IL-10 predominated in dogs with co-infection." (PMID 36739305, 2023). "We find that helminth co-infection enhances Salmonella colonization of the small intestine even in mice which lack IL-4, Stat6, and RAG1, and also in mice lacking eosinophils, and bacterial microbiota-depleted mice." (PMID 33471793, 2021).
Crohn disease (2 papers, 2012 to 2016). A gastrointestinal disorder characterized by chronic inflammation involving all layers of the intestinal wall, noncaseating granulomas affecting the intestinal wall and regional lymph nodes, and transmural fibrosis. "Genotypic and allelic distribution of STAT6 rs324015 polymorphism in Malaysian Crohn’s disease (CD) patients and control individuals." (PMID 27069792, 2016).
diabetes (2 papers, 2019). "To investigate this phenomenon further, we considered the possibility that changes in the islet milieu associated with the development of diabetes might be involved in promoting the loss of STAT6." (PMID 30338340, 2019). "Macrophage function is always impaired in patients with diabetes, such as STAT-6-mediated M2 polarization." (PMID 31886281, 2019).
diabetic kidney disease (2 papers, 2022 to 2026). Progressive kidney disorder caused by vascular damage to the glomerular capillaries, in patients with diabetes mellitus. "In diabetic kidney disease where autophagy is dysregulated, STAT6 is upregulated." (PMID 36348405, 2022).
endothelial dysfunction (2 papers, 2022 to 2023). In vascular diseases, endothelial dysfunction is a systemic pathological state of the endothelium (the inner lining of blood vessels) and can be broadly defined as an imbalance between vasodilating and vasoconstricting substances produced by (or acting on) the endothelium.
esophageal cancer (2 papers, 2020 to 2021). A primary or metastatic malignant neoplasm involving the esophagus. "In line with this, we found that STAT6 regulates SNAI1, another typical marker of EMT, which has an important role in E-cadherin expression and that the levels of SNAI1 were inversely related with E-cadherin expression, as reported in esophageal cancer." (PMID 32244885, 2020).
fungal infection (2 papers, 2011 to 2022). "Utilizing a specific inhibitor and gene-deficient mice, we demonstrate that STAT6 is required for mycosis-induced sinus inflammation." (PMID 35281012, 2022). "Arg1 induction upon fungal infection was partially dependent on the IL-4Rα/STAT6 signaling axis." (PMID 21246055, 2011).
Glucose intolerance (2 papers, 2015 to 2019). Glucose intolerance (GI) can be defined as dysglycemia that comprises both prediabetes and diabetes. "IL-4 was used to treat diet-induced obese mice and protected them from weight gain and glucose intolerance by activating the STAT6 pathway." (PMID 31297120, 2019). "While the IL-4/STAT6 pathway has been consistently shown to be protective against glucose intolerance, the role of Th2 cells in this disease has been much less well defined." (PMID 26146464, 2015). "Administration of IL-4 to DIO mice protects them from weight gain and glucose intolerance in a pathway that involves STAT6 activation and PPARα suppression." (PMID 26146464, 2015).
hemangioma (2 papers, 2024 to 2025). A benign vascular lesion characterized by the formation of capillary-sized or cavernous vascular channels. "Vascular lesions (e.g., hemangiomas or lobular capillary hemangiomas) can show avid enhancement but typically lack characteristic spindle-cell morphology and STAT6 nuclear positivity." (PMID 41431481, 2025).